BCL11A (BCL11 transcription factor A)
Diseases named in the same sentence as BCL11A in open-access papers (continued):
Sharing a sentence is not in itself a finding about the gene and the disease.
COVID-19 (6 papers, 2022 to 2025). A disease caused by infection with severe acute respiratory syndrome coronavirus 2. "BCL11A is regarded as a potential therapeutic target for epilepsy and was identified in a study in the UK as an independent variant that significantly predisposes individuals to critical COVID-19." (PMID 37781245, 2023). "BCL11A was reported to be associated with adaptive and innate immunity, especially for dendritic cell and lymphoid development, and genome-wide association studies demonstrated that this gene is participated in immune-mediated inflammatory disease such as COVID-19 and autoimmune diseases." (PMID 36591247, 2022). "Further, FUMA analysis identified six overlapping genes, including SMEK2, PNPT1, EFEMP1, CCDC85A, VRK2, and BCL11A, shared between COVID-19 and epilepsy." (PMID 37781245, 2023). "Based on these observations we postulate that in contrast to adults, BCL11A through its regulation of HbF could possibly have a protective effect in neonates and babies, who were relatively less affected by severe COVID-19." (PMID 40240424, 2025). "Further, based on results from this study and the COVID-19 host genetics initiative and its update, we further highlight several other genes of interest for our COVID-19 severity hypothesis, namely BCL11A, SLC22A31, SLC6A20, SLC2A5 and HBBP1." (PMID 40240424, 2025). "In addition, recent genome-wide association studies (GWAS) have identified several SNPs, including the BCL11A (rs1123573) and TAC4 (rs77534576) genes, that are associated with COVID-19 severity." (PMID 37112884, 2023). "Of these, 6 genes were found to be shared between COVID-19 and epilepsy, including SMEK2, PNPT1, EFEMP1, CCDC85A, VRK2, and BCL11A, all located on chromosome 2." (PMID 37781245, 2023).
diabetes (6 papers, 2014 to 2023). "Thus, an increased level of islet BCL11A expression was linked to established diabetes and impaired insulin secretion." (PMID 30242153, 2018). "Possibly, reduced BCL11A expression could also affect survival of other cell types, including β-cells, and thereby diabetes risk." (PMID 25517766, 2014). "Two of these DW genes have previously been reported to be associated with obesity and diabetes, respectively: the NUCB2 gene and the BCL11A gene." (PMID 25071839, 2014). "Sub-chronic exposure to elevated glucose levels stimulated BCL11A expression in primary human islets from cadaveric donors without diabetes, providing evidence that external cues could also influence islet BCL11A levels." (PMID 30242153, 2018). "The sample size of the PaC cases and controls without diabetes (448 cases and 557 controls), was likely underpowered as well, but our findings on DGKB-TMEM195 rs2191348, KCNQ1 rs231362, ADCY5 rs2877716 and BCL11A rs243021 may warrant further evaluation from larger studies." (PMID 25658847, 2015).
Dias-Logan syndrome (6 papers, 2021 to 2025). "Combining cytogenetics, molecular analyses, clinical data, and HbF monitoring, this de novo translocation was considered pathogenic, suggesting Dias-Logan syndrome in the patient caused by BCL11A haploinsufficency." (PMID 39941010, 2025). "Patient 1 exhibited a balanced reciprocal translocation disrupting the BCL11A gene, associated with Dias-Logan syndrome." (PMID 39941010, 2025). "Variants in BCL11A underlie Dias-Logan syndrome, which includes variable dysmorphic features and persistent fetal hemoglobin (fHb) (OMIM # 617101)." (PMID 33710394, 2021). "In Patient 1, OGM precisely delineated a translocation disrupting BCL11A, linking it to Dias-Logan syndrome and extending the understanding of its phenotypic spectrum." (PMID 39941010, 2025). "The region also contains 14 OMIM disease genes, two of which EFEMP1 (OMIM: 601,548) and BCL11A (OMIM: 606,557) are dominant and associated with the Doyne honeycomb degeneration of retina (OMIM: 126,600) and with the Dias − Logan syndrome (OMIM: 617,101), respectively." (PMID 36807877, 2023). "As such, variants in noncoding regions that can be relevant for genetic disease, such as variants in the enhancers of BCL11A and PTF1A that cause Dias-Logan syndrome (OMIM 617101) and pancreatic agenesis (OMIM 609069), respectively, were not covered in our analysis." (PMID 34078906, 2021). "BCL11A-related Intellectual Developmental Disorder (BCL11A-IDD), also known as intellectual developmental disorder with persistence of fetal hemoglobin [OMIM #617101] or Dias-Logan syndrome, is an autosomal dominant condition caused by heterozygous pathogenic variants in BCL11A (HGNC:13221)." (PMID 39448799, 2025).
Obesity (6 papers, 2014 to 2019). Accumulation of substantial excess body fat. "This has been done for a handful of disorders such as the FTO (fat mass and obesity-associated) locus in obesity, LMO1 (LIM domain only 1) in neuroblastoma predisposition and BCL11A (B-cell lymphoma/leukaemia 11A) in sickle cell anaemia [116•]." (PMID 27628759, 2016).
prostate carcinoma (6 papers, 2019 to 2023). A carcinoma that arises from epithelial cells of the prostate gland. "The results prompted that down regulated expression of BCL11A inhibited the proliferation and invasion of neuroblastoma in vitro, which was similar to the results in NK/T lymphoma and prostate cancer." (PMID 35909289, 2022). "In prostate cancer, BCL11A was significantly down-regulated when FOXQ1 loss its function, and led to decreased proliferation, invasion and increased apoptosis in prostate cancer cells." (PMID 31654056, 2019). "In prostate cancer, FOXQ1 regulated the expression of BCL11A/MDM2 to promote cell proliferation." (PMID 33748185, 2021).
anemia (5 papers, 2014 to 2024). A reduction in the number of red blood cells, the amount of hemoglobin, and/or the volume of packed red blood cells. "Individuals with the AG or GGgenotypes of the rs4671393 A/G BCL11A SNP are more likely to have ahigh concentration of BCL11A, which leadsto a low level of fetal hemoglobin, andconsequently anemia." (PMID 35293553, 2022). "In this study, Bcl11a was constitutively expressed in the BM and liver under normal conditions, and its expression levels were unchanged even in animals with anemia." (PMID 26877876, 2016).
neuroblastoma (5 papers, 2019 to 2022). Neuroblastoma (NB) is the most common solid, extracranial childhood tumor. "Taken together, high expression of BCL11A was related to high-risk and poor prognosis of neuroblastoma." (PMID 35909289, 2022). "We found, amongst others, strong upregulation of Pbk, a kinase that was recently identified as a key LIN28B target driving the proliferation and self-renewal of neuronal stem cells as well as Bcl11a, previously shown to be overexpressed in high-risk neuroblastoma." (PMID 34638267, 2021). "Moreover, the expression level of BCL11A is significantly elevated in high-risk neuroblastoma." (PMID 35909289, 2022). "This study provided new evidence of tumorigenesis of BCL11A by promoting neuroblastoma cell proliferation and metastasis." (PMID 35909289, 2022). "Amongst these genes were neuroblastoma-associated genes NTRK1, BCL11A, TH and CHGB, as well as HMX1, a transcription factor on chromosome 4 that is a master regulator of neural crest development." (PMID 36071103, 2022). "In conclusion, this study clarified the high expression level of proto-oncogene BCL11A in neuroblastoma tumor tissue." (PMID 35909289, 2022). "The current mechanism research in neuroblastoma was limited to the role of BCL11A in cell apoptosis." (PMID 35909289, 2022). "What’s more, the biological role of BCL11A in neuroblastoma was checked by silencing the BCL11A expression in neuroblastoma cell lines to explore its mechanism of tumor progression in NB." (PMID 35909289, 2022). "Down-regulation of BCL11A can induce apoptosis and inhibit proliferation in neuroblastoma cells." (PMID 31654056, 2019). "Although there was a previous study suggesting the possible association of BCL11A expression with high-risk neuroblastoma by database mining, our study further demonstrated the prognostic value of BCL11A in NB patients for the first time." (PMID 35909289, 2022).
schizophrenia (5 papers, 2015 to 2025). A major psychotic disorder characterized by abnormalities in the perception or expression of reality. "BCL11A is implicated in the aetiology of the schizophrenia, and the phenotypes associated to SNPs in the same LD block fit with the role of the BCL11A gene." (PMID 31616042, 2020). "Interestingly, BCL11A, a zinc finger protein that regulates transcription, showed decreased co-expression in multiple schizophrenia cohorts, in both peripheric and central nervous system, using machine learning to predict co-expression at the individual level." (PMID 34667144, 2021).
acute myeloid leukemia (4 papers, 2019 to 2025). Acute myeloid leukemia (AML) is a group of neoplasms arising from precursor cells committed to the myeloid cell-line differentiation. "In acute myeloid leukemia, high expression of BCL11A and MDR1 was significantly associated with the poor prognosis." (PMID 34938655, 2021). "In acute myeloid leukemia, high BCL11A expression is associated with a poor response to chemotherapy and promotes the proliferation and engraftment of TRIB1-expressing acute myeloid leukemia cells in vitro and in vivo." (PMID 39857257, 2025).
autism spectrum disorder (4 papers, 2016 to 2025). A spectrum of developmental disorders that includes autism, and Asperger syndrome. "Peculiarly, BCL11A was previously reported as a genome-wide risk gene for COVID-1949 and as a pleiotropic gene for attention-deficit/hyperactivity disorder, autism spectrum disorder and intelligence." (PMID 37286376, 2023). "CHD8 and BCL11A are also both expressed in the brain and play important roles in autism spectrum disorders." (PMID 40328966, 2025).
epilepsy (4 papers, 2022 to 2024). A brain disorder characterized by episodes of abnormally increased neuronal discharge resulting in transient episodes of sensory or motor neurological dysfunction, or psychic dysfunction. "A common variant of BCL11A has recently emerged as a general risk factor for epilepsy and drug resistance." (PMID 38927072, 2024). "This study aimed to evaluate the genetic association of BCL11A with the susceptibility to develop epileptic seizures and therapeutic response of patients with epilepsy in Han Chinese." (PMID 36568279, 2022). "Two de novo BCL11A heterozygous variants were reported to be associated with patients with epileptic encephalopathy, and it also indicated that a de novo mutation in the BCL11A gene result in epilepsy." (PMID 36568279, 2022). "We performed a two-stage case–control study to evaluate the associations between BCL11A SNPs and epilepsy." (PMID 36568279, 2022). "Similarly, mutations in potential epilepsy risk genes, like BCL11A/B, leading to neurodevelopmental delay and intellectual disability syndrome, are often but not always accompanied by epileptic seizures." (PMID 38927072, 2024). "Although we conducted genetic association analysis, genetic interaction analysis, eQTL analysis and PPI analysis and found that the BCL11A may be associated with the risk of epilepsy and therapeutic response of patients with epilepsy in Han Chinese." (PMID 36568279, 2022). "In this study, we analyzed BCL11A SNPs to explore their potential associations with epilepsy risk and therapeutic response of patients with epilepsy, and then performed expression quantitative trait loci (eQTL) analysis to investigate effects of identified SNPs on BCL11A expression." (PMID 36568279, 2022). "However, the association between the common BCL11A SNPs and epilepsy and the association between the common BCL11A SNPs and therapeutic response of patients with epilepsy in Han Chinese remain unclear." (PMID 36568279, 2022). "MDR analysis of BCL11A SNPs showed different interactions for therapeutic response of patients with epilepsy." (PMID 36568279, 2022). "Our results showed that rs2556375 regulates the expression of BCL11A in human brain tissue, especially in brain tissue of patients with drug-resistant epilepsy, which further demonstrates what we found in genetic association studies." (PMID 36568279, 2022). "Rs2556375 may increase the risks of epilepsy and drug resistance by regulating BCL11A expression in human brain tissues." (PMID 36568279, 2022). "Furthermore, protein–protein interaction(PPI) analysis was performed to further evaluate the role of BCL11A in epilepsy treatment." (PMID 36568279, 2022). "Among all the tagging SNPs, rs2556375, rs6747099, rs356977, rs10189857, rs12477097and rs13018474 in BCL11A also showed associations with epilepsy or therapeutic response of patients with epilepsy, but the association did not exist after Bonferroni correction." (PMID 36568279, 2022). "Furthermore, the results of PPI analysis verify the role of BCL11A in epilepsy treatment." (PMID 36568279, 2022). "However, the role of common BCL11A single nucleotide polymorphisms(SNPs) in therapeutic response of patients with epilepsy has not been evaluated, and the role of common BCL11A SNPs in epilepsy in Han Chinese remains unknown." (PMID 36568279, 2022).
lung squamous cell cancers (4 papers, 2013 to 2025). "Thus, future studies should assess whether BCL11A functions as an oncogene or tumor suppressor gene in NSCLC, whether BCL11A can be a better diagnostic and prognostic biomarker of early stage squamous cell lung cancer." (PMID 23758992, 2013). "BCL11A was also reported to be amplified in lung squamous cell cancer (SCC), with amplification more common among SCC samples of NSCLC without metastases." (PMID 32266150, 2020). "Recently, it was reported that BCL11A was amplified in lung squamous cell carcinoma (SCC), and this amplification was significantly more frequent in SCC samples of NSCLC patients without metastases." (PMID 23758992, 2013).
lymph node metastasis (4 papers, 2017 to 2023). "In our study, advanced III and IV stage LSCC patients had a dramatically higher BCL11A SNP OR than did those in initial I and II stage LSCC; and the rs4671393 AG/GG genotypes increased the risk of lymph node metastasis." (PMID 28225775, 2017). "Moreover, in patients of advanced laryngeal carcinoma and in those with lymph node metastasis LSCC, a higher OR of rs11886868 C/T and rs4671393 A/G polymorphisms and higher BCL11A plasma levels were discovered." (PMID 28225775, 2017). "BCL11A rs11886868 and rs4671393 genotype variations and correspondingly high BCL11A plasma levels are related to LSCC, besides, differences in plasma levels and genotype distribution may be related to lymph node metastasis status and the stage of LSCC." (PMID 28225775, 2017). "The plasma BCL11A concentrations in lymph node metastasis LSCC patients (131.22μg/L) were higher than those in no lymph node metastasis LSCC patients (75.99μg/L, P = 0.011)." (PMID 28225775, 2017). "Moreover, the plasma BCL11A concentrations at advanced stages were significantly higher than those at initial stages; the plasma BCL11A concentrations in lymph node metastasis patients were higher than those in no lymph node metastasis patients." (PMID 28225775, 2017).
breast tumor (3 papers, 2020 to 2025). "Recently, BCL11A was found amplified in nearly 40% of basal-like breast tumors." (PMID 34865122, 2021).
Burkitt lymphoma (3 papers, 2006 to 2021). A rare form of malignant mature B-cell non-Hodgkin lymphoma. "Among the main oncogenes induced in LCL-AT, we find BCL11A (log2FC 4.20), a modulator of transcriptional repression frequently upregulated in B-cell malignancies or TCL1A (log2FC 3.41), a survival promoting factor strongly associated with Burkitt lymphoma and related to other malignancies." (PMID 34183044, 2021). "MYC rearrangements in DLBCL can be partnered with IGH but, compared with Burkitt lymphoma, are more frequently partnered with the IGL or to non-IG genes such as BCL6, BCL11A, PAX5 or ICAROS49." (PMID 26416427, 2015).
Cognitive impairment (3 papers, 2016 to 2022). Abnormal cognition is characterized by deficits in thinking, reasoning, or remembering. "While the role of GPRASP1 on gene transcription is unknown, BCL11A haploinsufficiency has been associated with cognitive impairments." (PMID 36523271, 2022). "Overall, our data suggest that there is an ongoing molecular phenotype in Bcl11a-associated ID that is not restricted to early development and involves multiple post-natal molecular pathways underlying cognitive impairment and behavioral defects." (PMID 27453576, 2016).
endometrial cancer (3 papers, 2019 to 2023). Primary or metastatic malignant neoplasm involving the endometrium (mucous membrane that lines the endometrial cavity). "Concordant with an anti-cancer function, we found that endometrial cancer risk CVs were associated with decreased BCL11A expression in endometrial tumors." (PMID 31561579, 2019). "The only variant for which there was an indication of a specific association with non-endometrioid endometrial cancer was rs148261157 near the BCL11A gene." (PMID 32066633, 2020).
glioblastoma (3 papers, 2018 to 2022). The most malignant astrocytic tumor (WHO grade IV). "Early in 2012, as a potential oncogene, BCL11A has been reported to contribute to glioblastoma with specific expression pattern." (PMID 30322114, 2018). "Recent study showing that BCL11A may contribute to glioblastoma with specific expression patterns, which provide a helpful platform for future studies." (PMID 31654056, 2019).
Hodgkins lymphoma (3 papers, 2006 to 2023). A heterogeneous group of malignant lymphoid neoplasms of B-cell origin characterized histologically by the presence of Hodgkin and Reed-Sternberg (HRS) cells in the vast majority of cases. "In patients with Hodgkin lymphoma, bcl11a expression is found to be elevated and associated with EBV infection." (PMID 37868974, 2023). "Among the post-GC lines, the majority of multiple myeloma (MM) and Hodgkin's lymphoma (HL) samples were negative for BCL11A-XL." (PMID 16704730, 2006). "Among the post-GC lines, the majority of multiple myeloma and Hodgkin's lymphoma samples were negative for BCL11A-XL protein." (PMID 16704730, 2006).
lung adenocarcinoma (3 papers, 2018 to 2023). A carcinoma that arises from the lung and is characterized by the presence of malignant glandular epithelial cells. "Analysis of cancer genomics datasets revealed BCL11A to be upregulated in LUSC but not in lung adenocarcinoma (LUAD)." (PMID 30127402, 2018).
melanoma (3 papers, 2011 to 2025). A malignant, usually aggressive tumor composed of atypical, neoplastic melanocytes. "Melanoma cells were surface stained for TSPAN8, RELN and FXYD5 or intracellularly stained for renalase, CAPG, BCL11A and ID3." (PMID 21081927, 2011).
T-cell leukemia (3 papers, 2006 to 2025). A malignant disease of the T-lymphocytes in the bone marrow, thymus, and/or blood. "Lastly, BCL11A was not expressed in the majority of myeloid and T-cell leukemias." (PMID 16704730, 2006).
type 1 diabetes (3 papers, 2016 to 2023). "We did not replicate the findings that the associations near BCL11A, CENPW and THADA co-localise between the two diseases, despite overlapping samples and similar numbers of cases and controls in the type 1 diabetes GWAS." (PMID 33830302, 2021).